SLC8A1 (solute carrier family 8 member A1)
Diseases named in the same sentence as SLC8A1 in open-access papers (continued):
Sharing a sentence is not in itself a finding about the gene and the disease.
tumor (27 papers, 2016 to 2025). "From seven candidate NECSO regulators previously implicated in sodium homeostasis (NC1, CLT, DHPs, SLC12A2, SLC8A1, TRPM4, SLC9A1), intersection analysis identified two NECSO-associated DEGs - TRPM4 and SLC9A1 - showing consistent tumor-specific upregulation." (PMID 41235237, 2025). "The upregulated genes including GAB3, SLC8A1, KCNMA1, and ZNF471 following CFP1 knockdown, were expressed at low levels in tumor tissues and were associated with favorable prognosis of LUAD patients." (PMID 37735441, 2023). "Two TS-SLC genes, SLC29A1 (ENT1) and SLC8A1 (NCX1), are downregulated in tumor cells (TCS) via the EMT-induced zinc finger E box binding homology box 2 (ZEB2)/transforming growth factor (TGF)-BR/nuclear factor (NF)-kB pathway, or miR-223 in HCC, respectively." (PMID 36844876, 2023). "Few studies have reported the roles of MDH1 and SLC8A1 in NPC or explored the impact of their spatial distribution on the prognosis of tumor patients." (PMID 37151882, 2023). "An interesting study suggests that SLC8A1 gene-derived circSLC8A1 helps in the migration of MDSCs to the tumor site and enhances the tumor immune response." (PMID 35189921, 2022). "SLC2A1 encodes the glucose transporter, which is associated with the abnormal metabolism during cancer cell invasion, while SLC8A1 participates in the migration of tumor cells via regulating Na+/Ca2+ exchange, it is also involved in the endometrial tissue cellular heterogeneity." (PMID 34692538, 2021). "One study suggested that circSLC8A1, derived from the SLC8A1 gene, could act as a sponge of miR-494, which is crucial for migration of MDSCs into tumor site and regulation of the production of ARG1 and iNOS, thus enhancing the tumor immune response." (PMID 33613544, 2020). "We used multiplex immunofluorescence to verify the elevated expression of SLC8A1 and MDH1 in immune cell-enriched regions and tumor cell-enriched regions, respectively, both of which were associated with prognosis of NPC." (PMID 37151882, 2023). "However, there were no apparent associations between SLC8A1 expression and tumor invasion." (PMID 36231119, 2022). "Consistent with SLC8A1 expression being a surrogate of LKB1 activity rather than LKB1 expression itself, we observed higher SLC8A1 levels in liver metastases than in skin metastases with no significant changes in LKB1 expression." (PMID 37966164, 2023). "In the TCGA_LIHC cohort, 16 of 120 genes were downregulated in HCC tissue rather than in adjacent non-tumor tissue, and 9 of 16 genes, namely, ALDH8A1, C11orf96, CLYBL, EFNB3, ENG, NPC1L1, PIM3, SEC14L2, and SLC8A1, displayed a significant difference (p < 0.05)." (PMID 33352935, 2020). "Interestingly, consistent with the objective response of the right lower lobe lung mass and mediastinal/right hilar lymph nodes by imaging assessment, SLC8A1-ALK intergenic fusion could not be detected in peripheral blood, accurately reflecting the real-time tumor response to ceritinib therapy." (PMID 36042596, 2022).
cancer (26 papers, 2014 to 2025). A tumor composed of atypical neoplastic, often pleomorphic cells that invade other tissues. "In some human cancers, SLC8A1 expression was shown to be decreased, producing a corresponding reduction of intracellular calcium levels which leads to apoptosis evasion and more sustained proliferation rate." (PMID 26652480, 2015). "Analyzing gene expression and prognostic value in TCGA-COAD, we found that TCMM40L, SLC8A1, PPP1R3C, P2RX1 and HMX2 were significantly downregulated in cancer tissues." (PMID 40263288, 2025). "Although little is known about the prognostic role of SLC8A1 in CRC, potential is implied in several other cancers." (PMID 39385172, 2024). "CAIX does not only interact with HCO3− transporters in cancer cells, but is also closely colocalized with the Na+/H+ exchanger NHE1 and the Na+/Ca2+ exchanger NCX1 (SLC8A1), as shown by in situ PLA in hypoxic SiHa cells." (PMID 33804674, 2021). "We found several overlapping DEmRNAs that were involved in multiple pathways, such as SLC8A1, CAMK2B, and CACNA2D1, and have been demonstrated to play important roles in cancer pathogenesis." (PMID 31827401, 2019). "Although there are no evidences in literature about SLC8A1 expression level in HCC, a number of studies have described its lowered activity in other human cancers." (PMID 26652480, 2015).
cardiac disease (11 papers, 2013 to 2024). "Exercise training was found to reduce SLC8A1 expression in animals susceptible to heart diseases and SLC8A1 was associated with hand grip strength and bone density." (PMID 33588791, 2021).
infection (5 papers, 2020 to 2024). The state of being infected such as from the introduction of a foreign agent such as serum, vaccine, antigenic substance or organism. "SLC8A1/NCX1 is required for amplifying inflammatory and antimicrobial macrophage responses following high salt exposure and inhibiting its activity impairs high salt-induced inflammatory signaling, infection-triggered autolysosome formation and antibacterial activity." (PMID 36649035, 2023).
neurodegenerative disease (2 papers, 2024 to 2025). A disorder of the central nervous system characterized by gradual and progressive loss of neural tissue and neurologic function. "The upregulation of the Slc8a1 gene expressed in neurons and in rodent models of neurodegenerative diseases has been demonstrated to mediate microglia activation." (PMID 38891920, 2024).
SLC8A1 also shares sentences with these, for which no sentence is quoted: ischemia (22 papers); diabetes (12); Stroke (12); brain ischemia (11); breast carcinoma (7); glioblastoma (6); Alzheimer disease (5); Cerebral ischemia (5); pancreatic cancer (5); asthma (4); cardiac ischemia (4); atrial fibrillation (3); cardiac arrhythmias (3); cardiovascular disease (3); hepatocellular carcinoma (3); multiple myeloma (3); cervical cancer (2); epilepsy (2); esophageal cancer (2); gastric cancer (2); Hypercalciuria (2); hypoxic-ischemic encephalopathy (2); infarction (2); Insulin resistance (2); left ventricular hypertrophy (2); melanoma (2); Parkinson disease (2); primary pulmonary hypertension (2); prostate carcinoma (2); system lupus erythematosus (2).
A further 67 diseases each share a sentence with SLC8A1 in 2 papers or fewer.